PFKFB3 (6-phosphofructo-2-kinase/fructose-2,6-biphosphatase 3)
Description:
Catalyzes both the synthesis and degradation of fructose 2,6-bisphosphate.
Synonyms: IPFK2; PFK2; iPFK-2
Tractability: Small molecule: a structure with a bound ligand is known; a high-quality ligand is known; it has a high-quality binding pocket. PROTAC: ubiquitination databases record sites on it; its protein half-life has been measured; a small molecule that binds it is known.
Target class: Enzyme
Chemical probes: CHEMBL3421731
Gene: Protein-coding gene on chromosome 10 (6,144,928 to 6,254,644, forward strand). Ensembl gene ENSG00000170525.
Subcellular location (Human Protein Atlas): Nucleoplasm
Pathways (Reactome):
Metabolism: Regulation of glycolysis by fructose 2,6-bisphosphate metabolism
Gene Ontology:
Molecular function: 6-phosphofructo-2-kinase activity; protein binding; ATP binding; catalytic activity; fructose-2,6-bisphosphate 2-phosphatase activity
Biological process: fructose 2,6-bisphosphate metabolic process; gluconeogenesis; glycolytic process; positive regulation of glycolytic process; fructose metabolic process
Cellular component: 6-phosphofructo-2-kinase/fructose-2,6-biphosphatase complex; nucleoplasm; cytosol
Genetic constraint (gnomAD): Loss-of-function variants: 32 observed, 69.58 expected, observed/expected ratio (o/e) 0.46, 90% interval 0.35 to 0.62. The upper end of that interval is the gene's LOEUF score, 0.62, which puts it in group 2 of 6, group 1 being the genes least tolerant of losing a copy. Missense variants: 561 observed, 710.84 expected, observed/expected ratio (o/e) 0.79, 90% interval 0.74 to 0.85. Synonymous variants: 305 observed, 292.85 expected, observed/expected ratio (o/e) 1.04, 90% interval 0.95 to 1.14.
Homologues: Orthologues: macaque PFKFB3 (98% identical), chimpanzee PFKFB3 (97% identical), mouse Pfkfb3 (95% identical), rat Pfkfb3 (95% identical), guinea pig PFKFB3 (95% identical), dog PFKFB3 (94% identical), pig PFKFB3 (94% identical), rabbit PFKFB3 (92% identical), tropical clawed frog pfkfb3 (75% identical), zebrafish pfkfb3 (74% identical), Drosophila melanogaster Pfrx (51% identical), Caenorhabditis elegans pfkb-1.1 (46% identical), and 1 more. Paralogues in human: PFKFB2 (65% identical), PFKFB1 (62% identical), PFKFB4 (62% identical).
Diseases named in the same sentence as PFKFB3 in open-access papers:
PFKFB3 is named in the same sentence as 228 diseases in open-access papers, as found by Europe PMC text mining. Sharing a sentence is not in itself a finding about the gene and the disease. The quoted sentences say what the papers report.
breast cancer (80 papers, 2013 to 2026). A primary or metastatic malignant neoplasm involving the breast. "When PFKFB3 was silenced in paclitaxel‐resistant breast cancer cells, enhanced susceptibility of these cancer cells to paclitaxel was observed." (PMID 40956032, 2025). "As the primary cause of cancer-related deaths in females, chemoresistance in breast cancer is often associated with the abnormal expression of PFKFB3, such as in tamoxifen (TAM) resistance." (PMID 40264038, 2025). "We observed that the inhibition of tumor growth caused by Pfkfb3 deletion was less marked in the K-rasLA1 lung tumor model relative to the Erbb2 mammary tumor model." (PMID 39001392, 2024). "A BCSC transcriptome analysis of breast cancer showed high levels of PFKFB3, which is associated with metastatic activity in high-grade cancers (including TNBC and HER-2-enriched breast cancer)." (PMID 36831154, 2023). "Meanwhile, clear evidence shows that PFKFB3, when used as a key enzyme of glycolysis, is also notably elevated in liver cancer, osteoma, breast cancer and NSCLC, indicating the tight association of PFKFB3 with the prognosis of tumors." (PMID 34612136, 2021). "Constitutive activation of HER2 is a transcriptional driver of PFKFB3 in HER2+ breast cancer, with higher PFKFB3 mRNA being associated with a poorer progression-free survival." (PMID 34831136, 2021). "The association of Pfkfb3 with metastatic competency prompted us to investigate the relationship between Pfkfb3 expression and breast cancer development." (PMID 31413316, 2019). "Given the strong association of Pfkfb3 expression with breast cancer metastasis and aggressive disease states, we next sought to determine the impact of manipulating the expression and activity of Pfkfb3 on the outgrowth proficiency of D2-HAN derivatives." (PMID 31413316, 2019). "In breast cancer studies, coexpression of PFKFB3 and PFKFB4 was significantly associated with metastasis and chemotherapy resistance, suggesting that they may drive tumor progression through shared signalling pathways (such as the PI3K/AKT pathway)." (PMID 40438141, 2025). "HER2 expression, which is characteristic of many breast cancers, is associated with increased glucose metabolism mainly via the PFKFB3 pathway, suggesting it could represent a potential target of therapy." (PMID 33671514, 2021). "High PFKFB3 is associated with a larger reduction of IBTR after radiotherapy but PFKFB3 cannot reliably be used as a predictive marker of sensitivity to adjuvant radiotherapy in breast cancer." (PMID 40022029, 2025). "Trastuzumab-resistant human epidermal growth factor receptor 2 (HER2+) breast cancers drive glycolysis through 6-phosphofructo-2-kinase/fructose-2,6-biphosphatase 3 (PFKFB3)-mediated fructose-2,6-bisphosphate synthesis." (PMID 40725147, 2025). "Preliminary research has shown that the phosphorylation of PFKFB3 at Ser478 stimulates the proliferation and glycolysis of breast cancer cells." (PMID 40295451, 2025). "In conclusion, GSEA confirmed that PFKFB3 is significantly related to DNA repair, among other pathways, in breast cancer." (PMID 40022029, 2025). "A retrospective analysis in HER2 positive breast cancers showed that high levels of PFKFB3 mRNA correlated to shorter progression-free survival and distant metastasis-free survival." (PMID 40022029, 2025). "Phosphorylation of PFKFB3 at Ser478 in breast cancer cells stimulates glycolysis and cell proliferation." (PMID 40303296, 2025). "Recent research has demonstrated that PFKFB3 controls the cell cycle of breast cancer cells by downregulating p27 expression via AKT phosphorylation." (PMID 40295451, 2025). "The third enzyme in the family, PFKFB3, has shown to be abundant in several cancer types, including breast cancer." (PMID 40022029, 2025). "In this large, randomized breast cancer trial tumors with the highest PFKFB3 levels showed the largest reduction of IBTR after adjuvant radiotherapy." (PMID 40022029, 2025).
breast cancer (continued). "Further, more information regarding PFKFB3 in breast cancer is needed, to guide future potential inhibitory treatment." (PMID 40022029, 2025). "PFKFB3 is expressed at low levels in normal tissues but is significantly upregulated in various cancers (such as breast cancer and colorectal cancer), which is correlated with tumor invasiveness and poor prognosis." (PMID 40438141, 2025). "In summary, previous studies have shown that primarily RNA levels but also protein levels of PFKFB3 are prognostic in breast cancer." (PMID 40022029, 2025). "Fructose 2,6-biphosphatase 3 (Pfkfb3)High AutophagyLow phenotype was observed in metastatic breast cancer cells, whereas dormant breast cancer cells exhibited the Pfkfb3LowAutophagyHigh phenotype." (PMID 38291438, 2024). "The SHH signalling pathway was found to promote glycolysis and breast cancer progression by enhancing the expression of PFKFB3, a key enzyme in the glucose metabolism pathway of breast cancer cells." (PMID 38288377, 2024). "To simulate clinical conditions where a therapeutic intervention would be employed, we first examined the effects of Pfkfb3 deletion in a model of established oncogene-driven mammary tumor growth." (PMID 39001392, 2024). "For example, PIM2 mediates phosphorylation and stabilization of PFKFB3, leading to enhanced glycolysis and paclitaxel resistance in breast cancer cells." (PMID 37444501, 2023). "PFKFB3 overexpression decreased the survival period of breast cancer patients and was correlated with a number of clinicopathological parameters of breast cancer complicated with diabetes." (PMID 36973739, 2023). "The Kaplan–Meier plotter database was utilized to study the effect of PFKFB3 expression level on the survival of breast cancer patients." (PMID 36973739, 2023). "In conclusion, our study confirmed that PFKFB3 expression was correlated with the glucose level, lymph node metastasis, and tumor stage of breast cancer patients." (PMID 36973739, 2023). "Metastatic dormant breast cancer cells are typically autophagyhighPFKFB3low, and inhibition of autophagy in these cells induces metastatic reactivation by upregulating PFKFB3." (PMID 37444501, 2023). "Given the crucial role of PFKFB3 in breast cancer progression, GSEA (Gene Set Enrichment Analysis) was performed to further investigate the downstream signaling pathways." (PMID 36973739, 2023). "PFKFB3 is overexpressed in multiple solid tumors, including breast cancer, gastric cancer, colorectal cancer and pancreatic cancer." (PMID 36973739, 2023). "Among these isoforms, PFKFB3 expression is significantly elevated in breast cancer cells and correlates with poor clinical outcomes." (PMID 37444501, 2023). "Combining UALCAN with the CPTAC dataset, we analyzed PFKFB3 phosphorylation levels in five types of tumors (breast cancer, colon cancer, KIRC, LUAD, and UCEC)." (PMID 37253634, 2023). "So, we want to explore the potential link between PFKFB3 and the poor prognosis of breast cancer patients with hyperglycemia in this study." (PMID 36973739, 2023). "Aberrant expression of PFKFB3 is frequently found in breast cancer, colon cancer, pancreatic cancer, gastric cancer, liver cancer, and many other neoplasms." (PMID 37253634, 2023). "Our results indicated that the promoting effect of PFKFB3 on epithelial-mesenchymal transformation in breast cancer is compelling and the RAS/MAPK is especially a statistically recognized possible pathway." (PMID 36973739, 2023). "The overexpression of PFKFB3 was observed in breast cancer, colon cancer, non-small cell lung cancer (NSCLC), and hepatocellular carcinoma (HCC)." (PMID 37919747, 2023). "In terms of downstream mechanism exploration, we predicted and verified the cancer-promoting effect of PFKFB3 in breast cancer complicated with hyperglycemia through RAS/MAPK pathway." (PMID 36973739, 2023).
breast cancer (continued). "In this study, we demonstrated that the expression of PFKFB3 in breast cancer complicated with hyperglycemia was higher than that in breast cancer with euglycemia through cell experiment in vitro and histological experiment." (PMID 36973739, 2023). "BCAR4 acts together with the Hedgehog pathway effector GLI2 to upregulate HK2 and PFKFB3, which promotes proliferation and glucose uptake in breast cancer cells." (PMID 37204526, 2023). "Mechanistically, prolonged mitotic arrest activates AMPK, which phosphorylates and activates PFKFB3, resulting in the switch of breast cancer cells from oxidative respiration to glycolysis and sustained cell survival." (PMID 37444501, 2023). "Then, the mechanisms of PFKFB3 upregulation by high glucose concentration and PFKFB3 promoting the malignant phenotype of breast cancer were explored by online databases." (PMID 36973739, 2023). "The Kaplan–Meier plotter database and GEO database (GSE61304) was adopted to analyze the survival of breast cancer patients with different PFKFB3 expression." (PMID 36973739, 2023). "Our results suggested that PFKFB3 was overexpressed and promoted the proliferation as well as migration in breast cancer with diabetes." (PMID 36973739, 2023). "For other cancers, Pim-2 can promote glycolysis in some tumor cells by directly binding or changing the phosphorylation of PFKFB3 in breast cancer, PKM2 in HEK293T cells, and AMPKα in endometrial cancer." (PMID 36612063, 2022). "To further establish the relationship between miR-34a and tRiMetF31 and PFKFB3, we measured their levels in several breast cancer and brain cancer cell lines, with HMEC cells or normal brain tissue serving as a control." (PMID 35961977, 2022). "Among PFKFB isozymes, although PFKFB3 is a ubiquitous enzyme in normal cells and tissues, PFKFB3 is overexpressed in invasive tumor cells such as human pancreatic, colon, prostate, and breast cancer cells." (PMID 36077431, 2022). "Our findings demonstrate that tRiMetF31 profoundly suppresses angiogenesis by silencing PFKFB3, presenting a novel target for therapeutic intervention in breast cancer." (PMID 35961977, 2022). "A number of PFKFB3 inhibitors demonstrated efficacy in reducing tumor growth in several tumor models, including melanoma, lung, colon, pancreatic, gastric and breast cancers." (PMID 36733385, 2022). "Taken together, these results suggest that overexpressed PFKFB3 in breast cancer cells is a direct target of the miR-34a-guided, tRNAiMet-derived piR_019752-like fragment tRiMetF31." (PMID 35961977, 2022). "The meta-analysis indicated that PFKFB3 was overexpressed in breast cancer tissues, which was significantly correlated with tumor size and metastasis." (PMID 35961977, 2022). "In clinical cancers including lung cancers, osteosarcoma, and breast cancer, PFKFB3 expression indicates poor survival rates." (PMID 36077431, 2022). "The role of PFKFB3 has been reported in many cancers, including breast cancer, pancreatic cancer, and gastric cancer." (PMID 36016583, 2022). "A recent study has suggested that high expression of PFKFB3 indicates poor prognosis and enhances the self-renewal capacity of CSCs by in vivo extreme limiting dilution assays in breast cancer." (PMID 35155224, 2022). "PFKFB3 has been identified in many cancers, including breast cancer, pancreatic cancer, and gastric cancer." (PMID 36016583, 2022). "Another study has reported that AMPK activation increases glucose uptake, followed by an increase in lactate production by AMPK-dependent phosphorylation of PFKFB3 during mitotic arrest in breast cancer cells." (PMID 36359211, 2022). "miR-34a was downregulated, whereas tRNAiMet and PFKFB3 were upregulated in breast cancer, and elevated PFKFB3 significantly correlated with metastasis." (PMID 35961977, 2022). "Beyond glycolysis, PFKFB3 has been revealed to be involved in the cell cycle in breast cancer cells by degrading p27, which inhibits G1/S transition and promotes apoptosis." (PMID 35155224, 2022).
breast cancer (continued). "Regarding PFKFB3 expression in breast cancer tissues, numerous studies have been done with immunohistochemical staining, and we therefore performed a meta-analysis using data from these studies." (PMID 35961977, 2022). "In this study, using two breast cancer cell lines, HCC1806, and MCF7, we discovered that PFKFB3, which is overexpressed in breast cancer cells, is a direct target of the miR-34a-guided, tRNAiMet-derived piR_019752-like fragment tRiMetF31." (PMID 35961977, 2022). "In this study, we uncovered a novel 31-nt miR-34a-guided, tRNAiMet-derived, piR_019752-like fragment tRiMetF31 and revealed a crucial role of this fragment in suppressing the migration and angiogenesis of breast cancer via silencing PFKFB3." (PMID 35961977, 2022). "Concordantly, PFKFB3 is correlated with the aggressive features of breast cancer and indicates poorer prognosis in breast cancer and hepatocellular carcinoma." (PMID 35155224, 2022). "In lung adenocarcinoma cells, levels of PFKFB3 were downregulated after PFK15 treatment, and upregulated expression of PFKFB3 in breast cancer tissues assessed by immunohistochemistry was found to be associated with poor patient prognosis." (PMID 33922320, 2021). "Tumorigenesis associated with increased PFKFB3 transcription or with enhanced PFKFB3 phosphorylation has been shown to be implicated in ER+, PR+, HER2+, and recurrent breast cancer cells." (PMID 34831136, 2021). "PFKFB3 is frequently found in breast cancer, colon cancer, nasopharyngeal carcinoma, pancreatic cancer, gastric cancer, and many other neoplasms." (PMID 33671514, 2021). "In further studies, dormant breast cancer stem cells (BCSCs) exhibited strong autophagic flux, which resulted in downregulation of PFKFB3." (PMID 33671514, 2021). "On the other hand, autophagy induction causes a decrease in the levels of transcription factors triggering EMT, reduces 6-phosphofructo-2-kinase/fructose-2,6-biphosphatase 3 (Pfkfb3) expression and elicits metastatic dormancy in breast cancer stem cells." (PMID 34706732, 2021). "Cyclin-dependent kinase (CDK) 6 is also involved in PFKFB3 phosphorylation, but at the Thr463 and Ser467 residue sites in recurrent breast cancer." (PMID 34831136, 2021). "Dormant breast cancer cells express low levels of PFKFB3 but have high autophagic activity, while metastatic breast cancer cells display high levels of PFKFB3 but rather low levels of autophagy." (PMID 34207792, 2021). "This is supported by the fact that knockdown of ATGs in dormant breast cancer cells led to the stabilization of PFKFB3." (PMID 34207792, 2021). "High levels of estradiol, BRAFV600E, or epidermal growth factor (EGF), which are associated with breast cancer, melanoma, and non-small cell carcinoma (NSCLC), respectively, were found to regulate PFKFB3 expression." (PMID 33671514, 2021). "An inhibitory effect on Akt phosphorylation was also observed after PFKFB3 silencing in a breast cancer cell line, confirming the potential of PFKFB3 inhibitors to act as metabolic regulators." (PMID 33922320, 2021). "Study has shown that inhibition of PFKFB3 can inhibit the proliferation, migration and invasion of breast cancer cells (MDA-MB-231 and MDA-MB-468), and induce cell cycle G1 and S phase in vitro arrest." (PMID 34922556, 2021). "The 3-(3-pyridinyl)-1-(4-pyridinyl)-2-propen-1-one (3-PO) is a selective PFKFB3 inhibitor and has been found to inhibit the growth and glycolysis of lung cancer and breast cancer both in vivo and in vitro." (PMID 32631382, 2020). "Of note, PFKFB3 is a target of estrogen action in breast cancer cells, which have high glycolytic rates similar to endothelial cells." (PMID 33390959, 2020). "To clarify the role of compression-induced upregulation of ENO2, HK2, or PFKFB3 genes in breast cancer progression, we investigated genetic alteration of the genes." (PMID 31428701, 2019).